MET (MET proto-oncogene, receptor tyrosine kinase)
Diseases named in the same sentence as MET in open-access papers (continued):
Sharing a sentence is not in itself a finding about the gene and the disease.
tumor (continued). "Particularly, AXL and MET cooperation, found in different tumor contexts, is correlated to increased tumor progression and migration." (PMID 33182542, 2020). "According to our results, specific changes in the protein expression of VEGFR3/FLT4, HGFR/MET, and SLUG/SNAI2 were associated with the EMP-like phenotype of tumor cells." (PMID 32899940, 2020). "We found that the triple combination (HGF antibody + c-MET inhibitor + G) effectively reduced tumour volume and, more importantly, eliminated metastasis even at an advanced stage of the disease." (PMID 32203220, 2020). "Depletion of lncRNA-TUG1 inhibits tumor growth through provoking ubiquitination of MET and subsequent degradation of MET in vitro and in vivo." (PMID 33148302, 2020). "The activation of c-MET by hepatocyte growth factor (HGF) worsen the malignant features of tumor cells which results in a higher rate of cells motility, proliferation, metastasis, and invasion." (PMID 32795296, 2020). "As we have previously explained, the HGF/MET signaling pathway is closely related to tumor immunity and, thus, researchers reconsidered an HGF/MET-targeted strategy for immunological stimulation and activation to obtain better tumor-killing effects." (PMID 32435640, 2020). "It has been shown that there were correlations between RON or MET expressions and tumor aggressiveness and reduced survival." (PMID 32795296, 2020). "Tumor-derived exosomes enhance tumorigenic potential, and metastatic potential by increasing the expression of MET oncogene in bone marrow progenitor cells from individuals with melanoma." (PMID 32595638, 2020). "MET inhibition has demonstrated important antitumor activity with the regression of human GBM tumor xenografts." (PMID 33375286, 2020). "The miR-199 family has emerged as tumor suppressors in HCC by targeting critical genes of MET, transmembrane glycoprotein, and mammalian target of rapamycin (mTOR) pathways." (PMID 32964027, 2020). "This ATP-competitive c-MET inhibitor has been used by Avan and his colleagues to demonstrate decreased tumor volume, prolonged survival, and increased blood and tissue concentrations of gemcitabine in orthotopic models of PC." (PMID 33271944, 2020). "For instance, MET is closely related to tumor autophagy, metabolism, and microenvironment, all of which are not entirely dependent on the kinase activity of MET." (PMID 32435640, 2020). "Of the patients evaluated, four showed expression of the MET gene to be perturbed greater than one standard deviation from the mean degree of perturbation in the tumor-upregulated direction." (PMID 33205131, 2020). "The variants expressing NK4 and therefore lacking IDO were more susceptible to the cytotoxic effects of NK cells suggesting that c-MET can indirectly influence NK effects on tumor cells." (PMID 32117721, 2020). "Over the last few years, a plethora of studies have identified c‐MET as a potential target for GC tumours." (PMID 32686903, 2020). "miR-27b-3p has been confirmed to be a tumor suppressor, which represses proliferation and enhances apoptosis by targeting MET in DLBCL31." (PMID 33162801, 2020). "Although OC reduced the total c-MET expression level by 7.7-fold in A549-Luc tumor tissues, OC acts mainly as a competitive c-MET kinase inhibitor." (PMID 32545325, 2020). "Chromosomal amplification at 7q21-7q31 was reported to be closely related to tumor recurrence, and several oncogenes, such as MET and PEG10, in this region are amplified in many cancers." (PMID 32430013, 2020). "We have discussed the main MET inhibitors regarding their clinical trials and tumor effects in the following paragraphs, divided by each cancer drug section." (PMID 32575417, 2020). "Dysregulation of HSPG-regulated HGF/c-MET signaling in tumor microenvironment plays a key role in hepatocarcinoma." (PMID 32916872, 2020).
tumor (continued). "The role of c-MET expressing leukocytes in inflammatory, autoimmune, and neoplastic disease is of increasing interest, although the role of these cells in human disease is still incompletely understood." (PMID 32117721, 2020). "More recently a subpopulation of CD8 positive cytotoxic T-cell has been found to express MET, although at low levels, further linking its pathway to a role in tumor immunity." (PMID 32659961, 2020). "Other potential therapeutic targets to combat GBM chemoresistance include the phosphoinositide 3-kinase pathway, nuclear factor-κB, the hepatocyte/scatter factor (c-MET), the epidermal growth factor receptor, and the tumor microenvironment." (PMID 35582224, 2020). "Investigating the possible role of the c-MET-HGF axis in the regulation of anti-tumor immune responses is therefore an area worthy of investigation." (PMID 32117721, 2020). "In summary, geniposide exerted a tumor suppressive role in DLBCL at least partially by regulating the HCP5/miR-27b-3p/MET axis." (PMID 33162801, 2020). "Despite the selection of MET FISH copy number ≥ 5, MET protein expression, as assessed by IHC, was relatively low across tumor samples." (PMID 31776899, 2020). "Circulating tumor (ctDNA) analysis demonstrated good correlation between high MET copy number by ctDNA and response to MET inhibitors." (PMID 32971757, 2020). "In this latter case, we stratified patients who presented EGFR mutation or MET, ROS1 or ALK translocation, herein defined as mutated (Mut+), and compared them to the levels of tumor-associated caspase-4." (PMID 33187551, 2020). "The critical role of HGF/c-MET pathway in exerting mitogenic and motogenic effects on tumour cells has been reported in several cancers." (PMID 33271944, 2020). "The majority of TANs expressed PD-L1 and neutrophils from within the tumor and tumor-draining lymph nodes expressed higher levels of c-MET than those found in the spleen." (PMID 32117721, 2020). "Here we demonstrate that MET targeting with the long-sc60 results in activation of the apoptotic program in MET-addicted tumor cells." (PMID 32245152, 2020). "In tumors with a cut-off value, ABN401 strongly inhibited c-MET activity and suppressed tumor growth in c-MET-driven models." (PMID 32549194, 2020). "In fact, PD-L1 expression was positively associated with MET gene amplification in 389 NSCLC samples and, in a separate study of 155 resected NSCLC tumour samples." (PMID 33396187, 2020). "In vitro and xenograft model experiments have verified that miR-410 repression attenuates tumor growth and invasion by inhibiting MET and AKT signaling." (PMID 32083078, 2020). "Administering c-MET inhibitors alongside adoptive T-cell therapy prevented neutrophil recruitment, improved tumor eradication and increased survival in mouse tumor models." (PMID 32117721, 2020). "In vivo experiments confirmed that c-MET inhibitors can significantly reduce the tumour weight of the RMG1 cell xenograft model in vivo and the OCCC PDX model." (PMID 32295618, 2020). "Another potential predictive biomarker that should be considered in future trials of MET inhibitors in glioblastoma is HGF expression by the tumor, based on preclinical data." (PMID 31776899, 2020). "On the other hand, MET overexpression is known to activate the MET-signaling pathway, promoting tumor cell growth, survival, migration, and invasion." (PMID 32102486, 2020). "Slit/Robo signaling can downregulate MET signaling, thereby countering the effects of HGF–MET interactions on the tumor cells." (PMID 32670371, 2020). "Another study shows that MET inhibition in GC tumours induces the ability of cancer cells to fix DNA damage and increases the effectiveness of the undergoing radiotherapy." (PMID 32686903, 2020).
tumor (continued). "Further research shows that circ-PDE8A promotes tumor cell growth by upregulation of MET, a tyrosine kinase receptor that is one of the key oncogenes in a subset of epithelial tumors including PDAC." (PMID 33324638, 2020). "In the GEO dataset, we found that MET expression levels were significantly higher in PDAC tumor tissue than in paracancerous tissue in the GEO32676 and GEO15471 datasets." (PMID 33226369, 2020). "Some studies have demonstrated that the HGF/MET axis-activated downstream PI3K signaling pathway plays an important role in tumor resistance to MET inhibitors." (PMID 32435640, 2020). "Blocking EGFR or MET alone for tumor suppression can lead to cell survival by activating other alternative pathways." (PMID 32070026, 2020). "Activation of the c‐MET signalling pathway acts as a tumour protective mechanism against DNA damage." (PMID 32686903, 2020). "Hepatocyte growth factor (HGF)/MET proto-oncogene- dependent nitric oxide (NO) release by neutrophils suppresses tumor growth." (PMID 32595638, 2020). "Crizotinib is believed to exhibit antitumor effects by inhibiting the kinases ALK, ROS1, and c-MET and suppressing the activation of these factors, tumor cell proliferation, and tumor angiogenesis." (PMID 32882995, 2020). "It has been demonstrated that the binding of hepatocyte growth factor (HGF), a growth factor secreted from tumor cells or surrounding interstitial tissue, to the HGF receptor (MET) induces the autophosphorylation of MET." (PMID 31820255, 2020). "The MET gene amplification, mutation, rearrangement, and protein overexpression all lead to an elevated MET protein kinase activity and tumor growth." (PMID 33255238, 2020). "For this aim, a cohort of healthy controls and cancer patients with different tumor types and metastatic stages were analyzed to detect MET CN by ddPCR." (PMID 32102486, 2020). "HGF produced by PSCs within the primary tumour is neutralised by the neutralising antibody, depriving its receptor c-MET (on cancer cells and endothelial cells), of ligand binding." (PMID 32203220, 2020). "To further examine the antitumor effect of tepotinib in high-MUC5B- and -c-MET-expressing GCs, we conducted an in vivo study using xenograft mice and found that tepotinib significantly inhibited tumor growth." (PMID 32825724, 2020). "The expression of p-HER2 and p-MET were scored accordingly for the 45 LUSC tumor specimens with MET genotyped and sequenced." (PMID 32214092, 2020). "Cabozantinib plays important roles in tumor cell proliferation and tumor neovascularization targeting MET, vascular endothelial growth factor receptor (VEGFR), AXL, and RET." (PMID 33194654, 2020). "MET‐targeted therapies, which include HGF‐neutralizing antibodies, MET‐down‐regulating antibodies, and MET tyrosine kinase inhibitors, are currently being exploited as powerful strategies to treat tumours (Comoglio, Trusolino, & Boccaccio, 2018)." (PMID 32133617, 2020). "HGF/c-MET signaling is positively involved in tumor development, especially in terms of cell invasion and metastasis." (PMID 33718111, 2020). "The anti-MET VHH pool against the whole MET ectodomain can effectively decrease MET phosphorylation and protein expression, and inhibit tumor cell proliferation, invasion, and tumor growth." (PMID 32435640, 2020). "Experiments confirmed that MET-specific inhibitors upregulate the expression of PD-L1, thereby compromising the tumor-killing effect of MET inhibitors." (PMID 32435640, 2020). "In this in vivo study, we presented a highly potent inhibitor of c-Met and its dose-responsive anti-tumor efficacy in tumors with c-MET-amplified NSCLC." (PMID 32028611, 2020). "Preclinical studies have demonstrated that MET inhibitors had highly efficient anti-tumor activity in some tumor types, including hepatocellular carcinoma." (PMID 32435640, 2020).
tumor (continued). "Cabozantinib is a multiple receptor tyrosine kinase inhibitor targeting MET (c‐MET), VEGFR2, RET, AXL, KIT and TIE‐2, which are implicated in tumor growth, metastasis and angiogenesis." (PMID 32789967, 2020). "MET/HGF hyperactivation is also related to resistance to EGFR-TKIs (tyrosine kinase inhibitors); HGF promotes the clonal selection of c-MET amplified tumor subpopulations, which confers them substantial growth advantage and invasive potential." (PMID 32575417, 2020). "In our study, we analyzed the expression profile of a receptor tyrosine kinase, MET, and the checkpoint protein PD-L1 in tumor cells." (PMID 32659961, 2020). "The HGF/c-MET axis plays a key role in many stages of the metastatic process, from cellular dissociation in the primary tumour to reassociation within metastatic sites." (PMID 33271944, 2020). "Obviously, these results reflect the distinct CTCs enrichment methodologies of the two platforms, and the importance of tumor lineage for the MET-CTC-assay, highly diverse in our cohort of patient." (PMID 32102486, 2020). "The MET proto-oncogene encodes the tyrosine kinase receptor for the HGF, which activates downstream mechanisms upon tumor proliferation, invasion, and anti-apoptotic signals." (PMID 32492896, 2020). "The HSPG-mediated signaling activation of HGF released in the tumor microenvironment and of its receptor c-MET promotes ECM remodeling, inflammation, migration, angiogenesis, and invasion." (PMID 32916872, 2020). "SF/HGF and its receptor tyrosine kinase c-MET are expressed in brain tumors and were shown to promote tumor proliferation, migration, invasion, and angiogenesis." (PMID 32152825, 2020). "TNF-α produced by tumor cells induced c-MET expression in neutrophils via activation of NF-kB, further illustrating how the prevailing cytokine milieu can ignite anti-tumor effector functions in neutrophils." (PMID 32117721, 2020). "Lastly, c-MET expression was also evaluated by IHC as increased c-MET aids in tumor progression and proliferation." (PMID 33168005, 2020). "It delivers cytotoxin MMAE directly to c-Met-positive tumor cells and has demonstrated antitumor activity in tumors without increased copy number of the MET gene." (PMID 33195182, 2020). "Intriguingly, emerging evidence has revealed that, in addition to its conventional function as an oncogene, the HGF/MET axis stands at the crossroads of tumor autophagy, immunity, and microenvironment." (PMID 32435640, 2020). "With regard to EMT, in tumours of mice treated with HGF antibody + c-MET inhibitor (Hi + Ci), expression of E-cadherin was increased, while the expression of vimentin was reduced indicating inhibition of EMT." (PMID 32203220, 2020). "MET activation in tumor cells mediates a variety of cellular functions, including cell proliferation, metastasis, and angiogenesis." (PMID 32659961, 2020). "TANs appeared to express c-MET which is essential for their recruitment at the tumor site and thereby activation of their anti-tumor function." (PMID 31616408, 2019). "In comparison with non-tumor tissues, c-MET was overexpressed in 91.3% of tumor tissue samples (21/23, p < 0.01)." (PMID 30850583, 2019). "Further, concomitant administration of cetuximab and MET inhibitor (JNJ-38877605) results in a more pronounced tumor regression compared to cetuximab monotherapy in vivo." (PMID 30927908, 2019). "MITF is a driver of melanin synthesis and can activate the transcription of MET, an important receptor tyrosine kinase involved in tumor cell growth and release of extracellular vesicles." (PMID 30823658, 2019). "According to bioinformatics analysis and both in vivo and in vitro experiments, exosomal circPTGR1 competed with MET interactions to target miR449a, leading to the dysregulation of tumor microenvironment and the promotion of HCC development." (PMID 31277663, 2019).
tumor (continued). "Based on these findings we predicted that inhibition of ERBB1/2/4 using neratinib or inhibition of c-MET using crizotinib would block compensatory survival signaling and enhance the anti-tumor efficacy of [pazopanib + entinostat]." (PMID 31380285, 2019). "We then compared proteomic results and found higher frequencies (false-discovery rate-adjusted q-value < 0.05, logistic regression) in ERCC1, TOP1 and MET protein expression in metastatic lesions compared with primary tumours." (PMID 31292535, 2019). "The findings from the TCGA and CCLE analyses indicated that the positive correlation of PD-L1 and MET depends on the cellular origin of the tumor and the tumor microenvironment." (PMID 31480591, 2019). "Our subcutaneous xenograft studies evaluated comparative antitumor effects of lapatinib and foretinib monotherapy as well as combination therapy in HER2 and MET co-activated OE33 EAC tumor xenografts." (PMID 31772236, 2019). "Clinical trials of c-Met inhibitors typically select patients on the bases of tumor type, MET amplification, or c-Met protein overexpression." (PMID 30719213, 2019). "The suppressor of cytokine signaling 1 (SOCS1) was recently shown, in HCC lines, to regulate the HGF signal; SOCS1 inhibited the HGF-induced MET-mediated cell growth/proliferation, the invasion of the extracellular matrix, and the dissemination of tumor cells." (PMID 31781608, 2019). "In summary, heightened HGF/MET signaling is critical for tumor formation and progression in Tpl2 −/− mice." (PMID 30631034, 2019). "Similar to that described for the experiments with sorafenib, tumor growth was monitored in AKT/c-MET mice until 4 weeks after injection." (PMID 31277283, 2019). "Decreased CDK2 activity and the increased presence of p21CIP1 in anti-CDK2 precipitates were consistently observed in multiple tumour cell lines subject to combined MET and CDK4 inhibition." (PMID 31296956, 2019). "To test if CDK4/6 inhibition combined with MET inhibition is a feasible strategy for cancer treatment in vivo, we assessed the combined effect of crizotinib and palbociclib on the growth of human tumour xenografts in athymic mice." (PMID 31296956, 2019). "Currently, exosomal circ-PDE8A was reported to be associated with tumor progression and lymphatic invasion by the miR-338/MACC1/MET pathway in pancreatic ductal adenocarcinoma." (PMID 31277663, 2019). "The aim of this study was to explore the expression of c-MET in corresponding non-tumor and tumor tissues from CC patients, and its relationship with numerous clinicopathological factors." (PMID 30850583, 2019). "In the present study, c-MET overexpression was found in CC tumor tissues compared with non-tumor tissues." (PMID 30850583, 2019). "In summary, our findings demonstrate that combined PD901/MLN0128 treatment strongly inhibits tumor growth in AKT/c-MET mice and HCC cell lines." (PMID 31277283, 2019). "In this study, based on our in vitro and in vivo results and literature data, we introduce a novel, comprehensive network of common tumor-related proteins, such as PD-1, MET, RAF1, STAT3, BCL2, or mTOR." (PMID 31681332, 2019). "The migration response to MET activation contributes to the biological basis of invasion and metastasis in various neoplasms, and the cell survival response mediates drug resistance." (PMID 31040922, 2019). "Consistently, either pharmacologic or genetic targeting of lactate metabolism in tumor cells isolated from resistant xenografts completely prevents the onset of resistance to MET inhibition upon subcutaneous re-injection." (PMID 30927908, 2019). "Although a positive and causal relationship between MET and PD-L1 expression has been reported for in some cancer types, little is known about the functional role of MET in tumor immune evasion." (PMID 31480591, 2019). "In one recent study, NEAT1 suppressed miR-335 expression and facilitated tumor growth and invasion via disinhibition of MET." (PMID 31645479, 2019).